GPX4 (glutathione peroxidase 4)
Diseases named in the same sentence as GPX4 in open-access papers (continued):
Sharing a sentence is not in itself a finding about the gene and the disease.
endothelial dysfunction (6 papers, 2018 to 2025). In vascular diseases, endothelial dysfunction is a systemic pathological state of the endothelium (the inner lining of blood vessels) and can be broadly defined as an imbalance between vasodilating and vasoconstricting substances produced by (or acting on) the endothelium. "Emerging studies have indicated that hexadecanedioate may impact mitochondrial function and contribute to mitochondrial dysfunction, which is associated with oxidative stress through ROS/GSH/GPX4 pathway, inflammatory responses, and endothelial dysfunction." (PMID 40182922, 2025). "Therefore, we mainly focused on the association of miR-214-3p with GPX4 during ox-LDL-induced endothelial dysfunction." (PMID 34327240, 2021). "Downregulating miR-214-3p expression under ox-LDL conditions can protect VECs from ROS-induced endothelial dysfunction, likely by reversing the miRNA-mediated inhibition of GPX4 expression." (PMID 34327240, 2021). "Downregulation of miR-214-3p could protect VECs from ROS-induced endothelial dysfunction by reversing its inhibitory effect on GPX4 expression." (PMID 34327240, 2021). "In mouse aortic endothelial cells (MAECs), ox-LDL causes mitochondrial damage and decreases the expression of SLC7A11 and GPX4, whereas Fer-1 can suppress ox-LDL induced lipid peroxidation and endothelial dysfunction." (PMID 35906548, 2022). "In PFOS-induced vascular diseases studied here, ferroptosis-related pathways were activated, GPX4 was down-regulated, and ACSL4 was up-regulated, resulting in increased lipid reactive oxygen species levels, triggering iron death in endothelial cells and eventually leading to endothelial dysfunction." (PMID 36136468, 2022).
epileptic seizures (6 papers, 2019 to 2026). "Seizures, hyperexcitability, and loss of PV+ interneurons were also described in a mouse strain in which the selenocysteine residue in the active site of Gpx4 was genetically substituted with cysteine, resulting in a constitutive substantial loss of GPX4 catalytic activity." (PMID 30921410, 2019). "Collectively, these results indicate that lapatinib protects mice against ferroptosis in KA-triggered epileptic seizures via halting GPX4-dependent ferroptosis." (PMID 33362556, 2020). "And GPX4-mediated ferroptosis was involved in the neuroprotective effect of lapatinib in epileptic seizures." (PMID 33362556, 2020).
Insulin resistance (6 papers, 2023 to 2026). Increased resistance towards insulin, that is, diminished effectiveness of insulin in reducing blood glucose levels. "Meanwhile, previous studies reported that impaired antioxidant systems in adipocytes, such as the fat-specific deletion of glutathione peroxidase 4 (GPX4) or glutamate-cysteine ligase (GCLC), led to insulin resistance 58,59." (PMID 38653240, 2024).
kidney injury (6 papers, 2022 to 2026). Trauma to the kidney. "Gpx4−/− mice exhibit complete penetrant embryonic lethality, and conditional knockout of Gpx4 is associated with cancer, neurodegenerative diseases, acute kidney injury or liver injury, which can be prevented or mitigated by inhibiting ferroptosis." (PMID 38601472, 2024). "Furthermore, GPx4, a selenoprotein that directly reduces peroxidised phospholipids in the plasma membrane, serves as the central regulatory enzyme in ferroptosis; its deficiency in mice leads to ferroptosis in renal tubular cells and acute kidney injury." (PMID 41474210, 2026).
mastitis (6 papers, 2025). Inflammation of breast tissue during lactation or postpartum due to an obstructed duct or infection. "To investigate the effects of puerarin on ferroptosis in S. aureus-induced mastitis, we first determined ferritin and GPX4 expression in S. aureus-induced mastitis." (PMID 40693808, 2025). "In mice with mastitis induced by Staphylococcus aureus, the expression of NRF2 is significantly inhibited, and the expression of downstream target proteins (including SLC7A11 and GPX4) decreases, leading to ferroptosis and aggravated mastitis." (PMID 41413615, 2025). "In conclusion, Fer-1 alleviates K. pneumoniae-induced inflammatory factor activation and ferroptosis in BMECs via upregulation of the Nrf2/xCT/GPX4 pathway, supporting ferroptosis inhibition holds promise as a feasible therapeutic agent for the control of mastitis." (PMID 41343264, 2025). "In conclusion, GAP may inhibit S. aureus-induced mastitis in mice by triggering the Nrf2/SLC7A11/GPX4 signaling pathway and alleviating inflammation and ferroptosis." (PMID 39612214, 2025). "Similarly, Gardenoside alleviates S. aureus-induced mastitis by activating the Nrf2/SLC7A11/GPX4 signaling pathway, which reduces pro-inflammatory cytokines (TNF-α, IL-1β) expression and neutrophil infiltration." (PMID 41479924, 2025). "Furthermore, ferroptosis is a key factor in the pathogenesis of clinical mastitis in dairy cows, with numerous studies indicating that oxidative stress induces ferroptosis by promoting lipid peroxidation through GSH depletion and GPX4 inactivation." (PMID 41362615, 2025).
memory impairment (6 papers, 2022 to 2025). "Notably, Fer‐1 administration increased GPx4 levels, reduced MDA concentration and iron content, enhanced GPx4 expression in neurons, and attenuated brain loss/damage and learning and memory impairments." (PMID 36184790, 2022). "Unexpectedly, the object recognition memory was impaired after AAV–EGFP–Gpx4–miRNAi injection, indicating that Gpx4 may be associated with memory impairment." (PMID 35130906, 2022). "qRT-PCR revealed that in the hippocampus of CCI with memory impairment model rats 21 days after Fer-1 therapy, GPX4 and SLC7A11 gene expressions were dramatically increased." (PMID 35547819, 2022). "Moreover, we found the expression of SLC7A11 and GPX4 in the hippocampus of CCI-induced memory impairment using western blot." (PMID 35547819, 2022). "Consistent with the contributory effects of RSL3 or GPX4 knockdown on ferroptosis in hippocampal neurons, we found that RSL3 aggravated lipid peroxidation, iron overload, and memory impairment." (PMID 39350345, 2024). "We also discovered that ATF3 was considerably overexpressed in the hippocampal CA1 area, and gene markers of ferroptosis, such as GPX4, SLC7A11, SLC1A5, and PTGS2, were dysregulated in the CCI-induced memory impairment paradigm." (PMID 35547819, 2022). "Activation of SIRT1/Nrf2/GPx4 signaling following Res treatment represents a potential therapeutic strategy for inhibiting ferroptosis and ameliorating HIBI‐induced learning and memory impairments." (PMID 36184790, 2022). "qRT-PCR revealed that GPX4 and SLC7A11 gene expression were dramatically downregulated in the hippocampus of CCI with memory impairment model rats 21 days." (PMID 35547819, 2022). "We conducted behavioral tests to determine the involvement of SIRT1/Nrf2/GPx4 signaling in HIBI‐induced learning and memory impairments and assess its relationship to ferroptosis." (PMID 36184790, 2022). "Similarly, lipid peroxidation and gene markers (GPX4, SLC7A11, SLC1A5, and PTGS2) dysregulation of ferroptosis were discovered in the CCI-induced memory impairment model." (PMID 35547819, 2022). "Furthermore, the protein expressions of GPX4 and SLC7A11 in the hippocampus of CCI with memory impairment model rats 21 days were all considerably reduced, according to the western blot." (PMID 35547819, 2022).
multiple sclerosis (6 papers, 2020 to 2025). A progressive autoimmune disorder affecting the central nervous system resulting in demyelination. "Proanthocyanidin B2 alleviates cuprizone‐induced demyelination in mice by modulating the astrocytic xCT/GSH/GPX4 axis, reducing inflammation and oxidative stress, and protecting oligodendrocytes, offering a novel therapeutic strategy for multiple sclerosis." (PMID 40968556, 2025). "Treatment of oligodendrocytes with DRF led to upregulation of GPX4 for 12 h, aligning with the twice-daily administration of the drug in multiple sclerosis patients." (PMID 41146249, 2025). "Reduced expression of GPX4 mRNA in the gray matter of patients with multiple sclerosis and decreased GPX4 protein levels in mice with autoimmune encephalomyelitis have been convincingly demonstrated." (PMID 39619229, 2024). "Importantly, the need for buffering lipid peroxidation and ferroptotic cell death could be essential to promote chronic inflammation, as GPX4 expression is increased in patients suffering from multiples sclerosis." (PMID 38908072, 2024). "PCB2 can regulate the entire xCT/GSH/GPX4 axis of AS to reduce CPZ‐induced OL injury and demyelination, which may be a potentially effective drug for the treatment of multiple sclerosis." (PMID 40968556, 2025). "Moreover, decreased GPX4 and increased ACSL4 levels were noted in neurons of multiple sclerosis brains and spinal cord of EAE mice." (PMID 38908072, 2024). "In a multiple sclerosis model and in an experimental autoimmune encephalomyelitis (EAE) animal model, it has been observed that mRNA expression of the cytoplasmic, mitochondrial and nuclear GPx4 enzyme decreased in multiple sclerosis gray matter and in the spinal cord of EAE." (PMID 33233496, 2020). "This is a bit in contrast to the published finding that GPX4 protein levels show no changes in oligodendrocytes but in neurons in EAE and multiple sclerosis patients." (PMID 41146249, 2025).
Myocardial fibrosis (6 papers, 2021 to 2025). "Yueet al. reported significantly reduced SLC7A11 and GPX4 expressionin AF patients, reaffirming the integral role that ferroptotic activity plays inAF-related myocardial fibrosis and suggesting that such activity is mediated bythe xCT/GPX4 pathway." (PMID 39076535, 2024). "In stress overload-induced myocardial fibrosis, elabela and Fer-1 alleviate late concomitant myocardial fibrosis via the IL-6/STAT3/GPX4 signaling pathway." (PMID 39358326, 2024). "Consistent with the mRNA level, the expression of α-SMA, GPX4, and ACSL4 proteins indicated that inhibition of ferroptosis alleviated myocardial fibrosis induced by Ang II and PE in cardiomyocytes." (PMID 37288112, 2023).
tuberculosis (6 papers, 2022 to 2025). A chronic, recurrent infection caused by the bacterium Mycobacterium tuberculosis. "With this background information, we addressed whether mice displaying Gpx4 deficiencies are more susceptible to tuberculosis as a consequence of necrotic tissue pathology and the increased bacterial loads that are commonly associated with this outcome." (PMID 36069923, 2022). "It will be important to assess the role of these Gpx4 regulatory factors in host resistance to Mtb in pursuing this general approach for HDT of tuberculosis." (PMID 36069923, 2022). "Here, we demonstrate that patients with more severe tuberculosis display systemic downregulation of GPX4 expression along with lowered glutathione levels and, as expected, enhanced levels of lipid peroxidation." (PMID 36069923, 2022). "Here, we show that Gpx4 expression plays a major role in tuberculosis, regulating host resistance to infection as well as tissue pathology, and is required for the survival of Mtb-infected macrophages in vitro." (PMID 36069923, 2022). "Here, we document altered GPX4 expression, glutathione levels, and lipid peroxidation in patients with active tuberculosis and assess the role of this pathway in mice genetically deficient in or overexpressing Gpx4." (PMID 36069923, 2022). "As an initial step in evaluating the potential contribution of GPX4 in regulating lipid peroxidation as well as disease in tuberculosis, we analyzed elements of this pathway in TB patients in separate cohorts from Brazil and South Africa." (PMID 36069923, 2022). "The results presented here support an important role for the Gpx4-dependent glutathione metabolic pathway in the regulation of Mtb-induced necrosis and implicate this process as a potential target for host-directed therapy of tuberculosis." (PMID 36069923, 2022). "Together, our findings provide further evidence for the detrimental role of Gpx4-regulated necrosis in Mtb infection and identify the Gpx4/GSH antioxidant axis as a candidate target for host-directed therapeutic intervention in tuberculosis." (PMID 36069923, 2022). "Our study revealed a significantly upregulated lncRNA (lncRNA-cytoplasm-regulating ferroptosis and tuberculosis survival (CFTBS)) that modulates ferroptosis, enhancing M.tb intracellular survival by affecting the lipid peroxidation-related pathway rather than the cystine/GSH/GPX4 pathway." (PMID 41075263, 2025).
cerebral infarction (5 papers, 2023 to 2026). An ischemic condition of the brain, producing a persistent focal neurological deficit in the area of distribution of the cerebral arteries. "Our experiments unveiled reduced Fe2+ and 4HNE contents and enhanced GPX4 levels after overexpressing FTO in cerebral I/R models, along with reduced cerebral infarction and edema, and improved mitochondrial functions, as well as enhanced cell viability and weakened cell apoptosis in OGD/R neurons." (PMID 38430221, 2024).
Cirrhosis (5 papers, 2021 to 2024). A chronic disorder of the liver in which liver tissue becomes scarred and is partially replaced by regenerative nodules and fibrotic tissue resulting in loss of liver function. "In univariate analyses, both cirrhosis and GPC3 were identified as risk factors associated with HCC recurrence, whereas PSTK/GPX4 expression did not predict the prognosis of these HCC patients." (PMID 34983546, 2022).
cognitive decline (5 papers, 2021 to 2025). "Third, at the clinical interface, multicenter PD biobanks and retrospective cohorts should be established to validate the association of GPX4, ACSL4, and related biomarkers with motor progression and cognitive decline." (PMID 41425599, 2025). "They observed a decline in GPX4 expression in AD model mice and sufferers, indicating that substantial hippocampus nerve damage and cognitive decline may occur in GPX4 knockout mice." (PMID 38515787, 2024). "Moreover, iron levels positively correlate with cognitive decline in human subjects, and glutathione peroxidase (GPx4, also known as GPX4), the critical regulator of ferroptosis, is protective in AD mice model." (PMID 34987375, 2021). "Intramuscular administration of the iron chelator DFO has been shown to slow cognitive decline in AD patients, while high concentrations of MDA and 4-HNE—key lipid peroxidation products—and reduced expression of GPX4 have been detected across multiple brain regions in AD." (PMID 41425599, 2025).
colorectal adenocarcinoma (5 papers, 2022 to 2025). The most common type of colorectal carcinoma. "There was a positive correlation between PRDX5 and GPX4 levels in colorectal adenocarcinoma patients." (PMID 40831323, 2025). "On the other hand, a positive immunohistochemical reaction against GPx4 only in 41.4% and against GPx8 only in 29.3% of human colorectal adenocarcinoma specimens were observed." (PMID 35208621, 2022). "For instance, RBM15B- and IGFBP2-mediated GPX4 m6A modifications, along with NSUN5-mediated GPX4 m5C modifications, affect redox homeostasis, activate the STING pathway, and enhance anticancer immunity in colorectal adenocarcinoma (COAD)." (PMID 40176140, 2025).
cyst (5 papers, 2022 to 2025). A sac-like closed membranous structure that may be empty or contain fluid or amorphous material. "Because cyst(e)inase can promote ferroptosis by depleting intracellular cystine, the combination of cyst(e)inase or GPX4 inhibitor and PD‐L1 antibody can well inhibit tumour progression." (PMID 38652105, 2024). "It was found that baicalein up-regulated the mRNA expression of GPX4 in THP-1 cells pretreated with cyst fluid and iron." (PMID 36547083, 2022).
diabetic cardiomyopathy (5 papers, 2022 to 2026). Diabetic cardiomyopathy is a disorder of the heart muscle in people with diabetes. "The levels of the RNA methylase ALKBH5 and the ferroptosis marker GPX4 were significantly decreased in diabetic cardiomyopathy patients with myocardial tissue injury." (PMID 40548888, 2025). "Collectively, high-dose ALA suppresses ferritinophagy and activates the SLC7A11/GSH/GPX4 antioxidant axis via the AMPK-STAT3 signaling pathway to alleviate ferroptosis-induced diabetic cardiomyopathy." (PMID 41515376, 2025).
fibrosis (5 papers, 2021 to 2026). the formation of excess fibrous connective tissue in an organ or tissue in a reparative or reactive process. "In conclusion, the activation of TGF-β/Smad3 signaling is responsible for loss of GPX4 and the development of ferroptosis-associated fibrosis in the fibrotic kidney of patients and mice with CKD." (PMID 41079940, 2025).
gastric adenocarcinoma (5 papers, 2022 to 2025). "GPX4, a key regulator of ferroptosis, has been recognized as a prognostic biomarker for patients undergoing neoadjuvant chemotherapy, and is associated with the growth and metastasis of gastric adenocarcinoma." (PMID 40083663, 2025). "As assessed by IHC of patient tumor tissues, the cytoplasmic expression of both GSS and GPX4 was detected on tumor cells of gastric adenocarcinoma and PDAC, as well as in lymph nodal metastatic sites of PDAC." (PMID 39666242, 2024). "TIMER database analysis showed that the mRNA expression levels of GPx4 were different between tumour and adjacent normal tissues in a pan-cancer dataset, and GPx4 was overexpressed in stomach adenocarcinoma compared with adjacent normal tissues (P<0.01)." (PMID 36923926, 2023).
lipid metabolism disorders (5 papers, 2024 to 2025). "In this study, GA was shown to significantly reduce ferrous ion accumulation and PTGS2 expression, increase GPX4 expression, inhibit excessive ROS production, and attenuate lipid metabolism disorders." (PMID 41415578, 2025). "Previous investigations have confirmed that AMPK activation can inhibit lipid metabolism disorder-induced ferroptosis in macrophages by upregulating GPX4 expression." (PMID 40423448, 2025). "This study aimed to explore the role of ferroptosis in TBI, focusing on iron metabolism disorders, lipid metabolism disorders and the regulatory axis of system Xc−/glutathione/glutathione peroxidase 4 in TBI." (PMID 38250705, 2024). "Testicular iron overload, inactivation of the antioxidant enzyme GPX4, and lipid metabolism disorders contribute to the death of a significant number of cells associated with the male reproductive system, leading to reproductive disorders." (PMID 39545065, 2024).
lung diseases (5 papers, 2021 to 2026). "Our findings reveal that KF mitigates COPD progression by coordinately targeting the Nrf2/NCOA4/GPx4 axis to inhibit ferroptosis, providing a novel therapeutic strategy for oxidative stress‐driven pulmonary diseases." (PMID 41474210, 2026). "Specifically, high expression of SLC7A11 and GPX4 is a potential target for the treatment of lung diseases." (PMID 38562175, 2024). "Previous studies have elucidated that GPX4 is downregulated in many lung diseases, such as acute lung injury, radiation-induced lung fibrosis, and non-small cell cancer." (PMID 38030848, 2023). "Our findings not only elucidate the Nrf2/NCOA4/GPx4 axis as a previously unrecognised mechanism through which kaempferol counteracts smoke‐induced ferroptosis in COPD, but also highlight its potential as a multitarget phytotherapeutic agent for combating oxidative stress‐driven pulmonary diseases." (PMID 41474210, 2026).
multiple myeloma (5 papers, 2022 to 2025). "Nuclear localization of SREBP2 in myeloma cells was inhibited, accompanied by downregulation of isopentenyl pyrophosphate (IPP) and GPX4, after treatment with ART." (PMID 37859702, 2023). "More globally, analysis of GPX4 protein expression levels performed in up to forty different cancers show that besides AML, GPX4 is also elevated in most hematological malignancies including Acute Lymphoblastic Leukemia (ALL), Multiple Myeloma (MM) and Non-Hodgkin's Lymphoma (NHL)." (PMID 38977956, 2024).